COL4A1 (collagen type IV alpha 1 chain)
Diseases named in the same sentence as COL4A1 in open-access papers (continued):
Sharing a sentence is not in itself a finding about the gene and the disease.
glioma (continued). "In detail, COL1A1, COL1A2, COL3A1, COL4A1, and COL4A2 positively correlated with the infiltration of B cells, CD8+T cells, CD4+T cells, macrophages, neutrophils, and dendritic cells in low-grade glioma." (PMID 38969910, 2024). "In conclusion, the collagen genes (COL1A1, COL1A2, COL3A1, COL4A1, COL4A2, and COL5A2) could regulate the immunosuppressive microenvironment and be involved in the EMT process of glioma." (PMID 34034744, 2021). "COL4A1, COL4A2 could regulate the immunosuppressive microenvironment of glioma." (PMID 40351420, 2025). "However, COL4A1-2 and COL4A3-4 have completely opposite effects on glioma patient prognosis, which verified our hypothesis to a certain extent." (PMID 40351420, 2025). "Our findings for COL4A1 are also supported by recent reports demonstrating that its depletion impairs proliferation and invasion in hepatocellular carcinoma and glioma cells, although its specific role in STAD had not been well characterized prior to this study." (PMID 41291892, 2025). "Importantly, we identified that 6 collagen genes (COL1A1, COL1A2, COL3A1, COL4A1, COL4A2, and COL5A2) could regulate the immunosuppressive microenvironment of glioma." (PMID 34034744, 2021). "Thus, this part of results further confirmed the COL4A1-2 were positively related to glioma progress, while COL4A3-4 have a negative effect on glioma development." (PMID 40351420, 2025).
aneurysm (17 papers, 2011 to 2026). Bulging or ballooning in an area of an artery secondary to arterial wall weakening. "Variants of collagen genes, including COL4A2, have been implicated in sporadic AD pathogenesis, and COL4A1 and COL4A2 mutations are associated with a broader spectrum of cardiovascular, renal, ophthalmological, and muscular abnormalities as well as aneurysms." (PMID 41497804, 2025). "The lower amount of collagen IV in the descending aorta may explain the sensitivity to aneurysm formation as hemizygosity of Col4a1/a2 augments AAA formation in mice." (PMID 39195920, 2023).
hepatocellular carcinoma (17 papers, 2020 to 2025). A malignant tumor that arises from hepatocytes. "Prior research has also demonstrated a significant upregulation of COL4A1/2 in precancerous and hepatocellular carcinoma tissues." (PMID 38907304, 2024). "Co-treatment with KPA also decreased the expression of genes, regulating the progression of fibrosis (e.g., COL6A3, AEBP1, SPARC, TNC, LAMB1, BGN) and hepatocellular carcinoma (e.g., COL4A1, COL4A2, TUFT1, VCAN, NID1)." (PMID 39404414, 2024). "Specifically, elevated levels of COL4A1 were found in hepatic tumors, and it was shown to promote cell migration and invasion in hepatocellular carcinoma cells via the FAK-Src pathway." (PMID 37835389, 2023). "COL3A1 was reported to promote renal cell carcinoma growth and metastasis whereas COL4A1 facilitated hepatocellular carcinoma cells proliferation, migration and invasion by activating FAK-Src signaling." (PMID 36690975, 2023). "Overexpression of this transcription factor in hepatocellular carcinoma cells dramatically elevates COL4A1 expression while its knockdown in SMMC7721 and SK-Hep1 cells significantly decreases the COL4A1 expression level." (PMID 35356434, 2022). "Deregulated COL4A1 was identified in lots of tumors, such as esophageal squamous cell carcinoma, laryngeal squamous cell carcinoma, hepatocellular carcinoma, and bladder cancer, etc.." (PMID 35046992, 2021). "In hepatocellular carcinoma, elevated RUNX1 levels have been shown to upregulate COL4A1 expression, thereby activating the FAK-Src signaling pathway and promoting the proliferation, migration, and invasion of hepatocellular carcinoma cells." (PMID 38430423, 2024). "In hepatocellular carcinoma, RUNX1 induces tumor cell migration, invasion, and metastasis by activating the COL4A1/FAK/Src signaling axis." (PMID 38430423, 2024). "A study on hepatocellular carcinoma demonstrated that COL4A1 promotes growth and metastasis through the FAK-Src signaling pathway, providing insights into the function of COL4A1 in BC." (PMID 39529627, 2024). "For example, COL4A1 was overexpressed in hepatocellular carcinoma cells, and its upregulation stimulated FAK-Src signaling to boost hepatocellular carcinoma growth and metastasis." (PMID 35297303, 2022). "Likewise, other studies reported significantly upregulated expression of COL4A1 and COL4A2 in patients with liver cirrhosis and hepatocellular carcinoma." (PMID 36768808, 2023).
liver fibrosis (14 papers, 2012 to 2025). "Col4a1 is a hepatic fibrosis-associated gene, and the expression of its mRNA induces hepatic fibrosis, which can result in liver injury." (PMID 37834148, 2023). "COL4A1 has an established role in other fibrotic diseases including liver fibrosis, Goodpasture's syndrome, and Alport syndrome." (PMID 36404995, 2022). "Astonishingly, these findings are in line with seminal reports demonstrating that CXCL1, CXCL11, HIF1A, COL4A1, and FN1 are implicated in liver fibrosis." (PMID 32161843, 2020). "Furthermore, hepatic mRNA levels of fibrogenic genes (Acta2, Col1a1, Col3a1, Col4a1, Tgfb1, Mmp13 and Vim) were significantly upregulated in miR-223KO mice compared with WT mice, suggesting that miR-223 deletion accelerated liver fibrosis." (PMID 33867837, 2021). "Classical fibrotic mediators and markers (including Tgfb1, Timp1, and Vcam1), collagen of the ECM (including Col4a1, Col4a2, Col16A1, and Col18a1) and cell surface adhesion and signaling integrin (Itga2, Itga5) were found to be differentially expressed in the enriched hepatic fibrosis pathways." (PMID 39747668, 2025). "Interestingly, with development of bridging fibrosis at week 52, changes in pathways related to hepatic fibrosis/hepatic stellate cells activation decreased as compared to 24 weeks and were mainly limited to increase in genes for Col4a1, Mmp12, Mmp13 and Vcam1." (PMID 29222421, 2017). "Among the genes, further analysis disclosed that the gene expression levels of TLR2, Col1a1, Col1a2, Col4a1, Col4a2, and Pdgfr-β were changed during the SCU anti-liver-fibrosis process, and qRT-PCR verified this result." (PMID 40243656, 2025). "On the basis of transcriptomics and network pharmacology findings, genes connected with liver fibrosis and the PI3K/AKT signaling pathway, such as Col1a1, Col1a2, Col4a1, Col4a2, TLR2, and Pdgfr-β, were chosen for qRT-PCR validation." (PMID 40243656, 2025). "The significant enrichment of hepatic fibrosis/hepatic stellate cell activation (z = 0, p < 1e-5) largely due to the downregulation of several collagens (COL1A1, COL4A1, and COL4A2) was present in cluster 4 that contained nearly all control iAstros." (PMID 36590162, 2023). "Given that COL4A1 and COL4A2 were among the most upregulated collagens in human cirrhotic livers, we hypothesized that COL4 is regulated by TNF-α and has a role in liver fibrosis and PHTN." (PMID 38713515, 2024).
epilepsy (13 papers, 2018 to 2026). A brain disorder characterized by episodes of abnormally increased neuronal discharge resulting in transient episodes of sensory or motor neurological dysfunction, or psychic dysfunction. "There are certain phenotypic pointers to considering COL4A1/2 mutations in individual patients, with implications for individual patient management and for our understanding of epilepsy genetics." (PMID 30413629, 2018). "Indeed, we report for the first time post-operative seizure outcomes for six genetic causes of epilepsy: COL4A1, GRIN2B, NEXMIF, NSD1, SCN2A and SLC9A6." (PMID 37264783, 2023). "Interestingly, mutations in Col4a1 and Col4a2 can cause neuromuscular dysfunction, vascular defects, myopathies and neurological disorders including epilepsy and cortical malformations." (PMID 31615574, 2019). "The evidence so far, although limited, suggests that surgery may be a valid option for drug-resistant COL4A1/2-associated epilepsy." (PMID 30413629, 2018). "Broadening the spectrum of clinical phenotypes associated with COL4A1/COL4A2 mutations may help our understanding of the genetic architecture of the epilepsies." (PMID 30413629, 2018). "Thirty‐two percent of individuals with COL4A1/2 (123/390 and 13/41, respectively) were reported to have suffered a seizure or have epilepsy." (PMID 35699195, 2022). "COL4A1/COL4A2 mutations typically cause a severe neurologic condition and a broader spectrum of milder phenotypes, in which epilepsy is the predominant feature." (PMID 30413629, 2018). "An increased awareness of COL4A1/2-related epilepsy phenotypes has clinical and research implications." (PMID 30413629, 2018). "In our series of new and published patients, the neurologic patterns associated with COL4A1/COL4A2 mutations comprised a typical severe presentation and a spectrum of less common phenotypes, in which epilepsy can be the predominant feature." (PMID 30413629, 2018). "Epilepsy was another common phenotype in COL4A1/2, as suggested by OMIM and previous literature." (PMID 35699195, 2022). "Mutations associated with epilepsy were spread across COL4A1 and a clear genotype–phenotype correlation did not emerge." (PMID 30413629, 2018). "Third, the case report form was not specially designed for COL4A1 syndrome, so a mass of data related to multisystemic phenotypes, such as muscle cramps, epilepsy, and HANAC syndrome, were not collected." (PMID 35711275, 2022). "The epilepsy phenotypes associated with COL4A1/COL4A2 mutations suggest that this may not be the most comprehensive strategy to determine the full effect of genetic variation in the causation and biology of the epilepsies, or to best apply genetically driven precision medicine approaches." (PMID 30413629, 2018).
hemorrhagic stroke (12 papers, 2013 to 2025). A stroke caused by a bleed on the brain. "Overexpression of COL4A1 appears to interrupt the integrity of the basement membrane and cause both ischemic and hemorrhagic stroke." (PMID 34415564, 2022). "Patients with subcortical ischemic or hemorrhagic stroke and early-onset dementia are warranted to have genetic study for COL4A1 gene mutation." (PMID 34415564, 2022). "Since then, several researchers reported that mutation in COL4A1 gene results in human hemorrhagic stroke." (PMID 24156251, 2013). "This association is particularly interesting as rare mutations in COL4A2 and the closely related COL4A1 protein lead to small vessel disease and hemorrhagic stroke,28, –, 30 and common variants in close LD with this SNP (r2 > 0.8) have been linked to sporadic small vessel disease." (PMID 26674333, 2016). "However, further understanding of retinal vascular pathology could be useful in developing therapeutics to prevent hemorrhagic strokes in patients with COL4A1 and COL4A2 mutations." (PMID 26813606, 2016). "Moreover, a genetic disease associated with mutations in the COL4A1 gene and reduction in the expression of α1 subunit are associated with pathological alterations in microvessels and hemorrhage in mice, and have been linked to hemorrhagic stroke in humans." (PMID 25909592, 2015). "Mutations in COL4A1 or COL4A2 were contribute to a broad spectrum of disorders, including glaucoma, myopathy, and hemorrhagic stroke." (PMID 31736743, 2019). "Genome-wideassociation studies have identified several single nucleotide polymorphisms (SNPs)associated with sporadic hemorrhagic strokes, including APOE(19q13), SLC25A44 (1q22), COL4A1 (13q34) andKCNK17 (6p21)." (PMID 28153846, 2017). "Together, these findings suggested that patients with COL4A1 and COL4A2 mutations may be at a higher risk of retinal hemorrhages, and retinal examinations may be useful for identifying patients with COL4A1 and COL4A2 mutations who may also be at a higher risk of hemorrhagic strokes." (PMID 31484286, 2019). "Together, our findings suggest that patients with COL4A1 and COL4A2 mutations may be at elevated risk of retinal hemorrhages and that retinal examinations may be useful for identifying patients with COL4A1 and COL4A2 mutations who are also at elevated risk of hemorrhagic strokes." (PMID 26813606, 2016).
intracranial hemorrhage (12 papers, 2013 to 2026). Bleeding within the SKULL, including hemorrhages in the brain and the three membranes of MENINGES. "Perinatal brain hemorrhages in fetuses and newborns were the first manifestation of COL4A1 mutations to be described." (PMID 41001161, 2025). "Perinatal brain hemorrhages in fetuses and newborns have been described as the commonest manifestation of COL4A1 mutation." (PMID 39310498, 2024). "In recent years, a new foreign study reported that COL4A1 gene mutation was associated with perinatal intracranial hemorrhage, suggesting that hemorrhagic infarction may be related to genetic factors." (PMID 40666387, 2025). "The presence of cerebral microbleeds on brain MRI might help to identify those with COL4A1/COL4A2 mutations at highest risk of intracranial hemorrhage prior to anticoagulation or thrombolysis." (PMID 30413629, 2018). "Several authors have reported that mutations in COL4A1 may be the Mendelian cause of prenatal onset intracranial hemorrhage." (PMID 25124159, 2014). "The management of COL4A1 mutation patients involves a comprehensive approach, including detailed clinical assessments and molecular testing for COL4A1, especially in cases of unexplained brain hemorrhage, porencephaly, or eye abnormalities." (PMID 41001161, 2025). "The keywords “COL4A1” AND “perinatal intracranial hemorrhage” OR “neonatal intracranial hemorrhage” were also searched as entry terms." (PMID 38978838, 2024). "Disruptions of the genes, such as the COL4A1 and COL4A2 genes, are common genetic causes identified in fetal intracranial hemorrhage; however, the disruptions of the JAM3 gene are rarely reported." (PMID 36339007, 2022). "In our reported case, there were no anomalies observed in neuromuscular or cardiac development, and there were no signs of intracranial hemorrhage, phenotypes characteristic of pathogenic COL4A1 variants." (PMID 40317787, 2025). "This study presents a case series of term neonates affected by intracranial hemorrhage, with no apparent risk factors for the development of this condition, who were carriers of COL4A1 gene variants." (PMID 38978838, 2024). "PBA was given orally to Col4a1 mutant mice, and there was a reduced occurrence of intracranial hemorrhage, but kidney and ocular involvement was not improved." (PMID 36982595, 2023).
schizencephaly (11 papers, 2015 to 2025). "Of note, one mouse from one strain (Col4a1+/G1038S) presented SWI sensitive lesions along with schizencephaly, a radiological features associated with Gould syndrome." (PMID 41311701, 2025). "Recently, we found that mutations in COL4A1, which encodes type IV collagen alpha 1 subunit, cause schizencephaly accompanied by polymicrogyria in the adjacent cortex of the transmantle cleft as well as focal cortical dysplasia." (PMID 26052266, 2015). "Schizencephaly is also associated with mutations in COL4A1 and COL4A2." (PMID 37847489, 2024). "Venous tortuosity may be helpful in assessing for a possible relationship between schizencephaly and COL4A1 mutations." (PMID 37847489, 2024). "Several reports have shown porencephaly, schizencephaly, polymicrogyria and PVNH associated with COL4A1 pathogenic variants, which cause imbalance or structural distortion of the collagen IV triple helix." (PMID 32895508, 2020). "Additionally, schizencephaly, although rarely reported in individuals with Gould syndrome, was also detected with low incidence in Col4a1 mutant mice (one Col4a1+/G1038S mouse)." (PMID 41311701, 2025). "Individuals with COL4A1/2 were also reported to manifest with schizencephaly (8% [24/290] of individuals with COL4A1 and 13% [4/31] with COL4A2) and cerebellar atrophy (5% [14/290] of individuals with COL4A1 and 3% [1/31] with COL4A2)." (PMID 35699195, 2022).
glaucoma (10 papers, 2014 to 2024). Increased pressure in the eyeball due to obstruction of the outflow of aqueous humor. "To test the role of TGFβ signaling in glaucoma-relevant phenotypes, we genetically reduced TGFβ signaling using mice with mutated Tgfbr2, which encodes the common receptor for all TGFβ ligands in Col4a1+/G1344D mice." (PMID 38717426, 2024). "In some genetic contexts, Col4a1+/Δex41 mice have chronically dysregulated IOPs and optic nerve damage that mimic glaucoma and COL4A1 mutations can cause developmental glaucoma in patients." (PMID 28237965, 2017). "Mutations in the genes encoding type IV collagen alpha 1 (COL4A1) and alpha 2 (COL4A2) cause a multisystem disorder that includes ocular anterior segment dysgenesis (ASD) and glaucoma." (PMID 38717426, 2024). "We next sought to determine if Col4a1+/G1344D mice have retinal ganglion cell axon damage in the optic nerve consistent with glaucoma." (PMID 38717426, 2024). "We found that Col4a1+/G1344D mice have multiple pathological hallmarks of glaucoma and that Tgfbr2 heterozygosity partially prevents these phenotypes in Col4a1+/G1344D mice." (PMID 38717426, 2024). "Based on these parameters, future studies will seek to identify the developmental signaling pathways that are perturbed in periocular mesenchyme and the molecular mechanisms by which Col4a1 mutations cause ASD and glaucoma." (PMID 28237965, 2017). "Here, we tested whether altered TGFβ signaling also contributes to glaucoma-related phenotypes in Col4a1 mutant mice." (PMID 38717426, 2024). "Subsequently, COL4A1 mutations were identified in patients with a spectrum of ocular defects including ONH, microphthalmia, cataract, microcornea, Axenfeld-Rieger's anomaly, Peter's anomaly, high IOP and glaucoma." (PMID 28237965, 2017).
migraine (10 papers, 2019 to 2025). "Further protein structural or functional studies are needed to investigate this variant’s impact on COL4A1 function and migraine mechanisms." (PMID 40869943, 2025). "Some genes such as CACNA1A, NOTCH3, TREX1 and COL4A1 are associated with nystagmus or vasculopathies related to migraines." (PMID 37622929, 2023). "Forms of COL4A1 mutations include infantile hemiparesis, seizures, migraine with aura, single or recurrent intracerebral hemorrhages, eye symptoms and muscle spasms." (PMID 35741740, 2022). "The link between COL4A1 variants and migraine may arise from vascular dysfunction, blood-brain barrier (BBB) disruption, and neuronal excitability." (PMID 40869943, 2025). "Of note, hsa-miR-605-3p targets COL4A1, PNKD, TGFBR2, and YAP1, which have been identified as susceptible genes in migraine patients." (PMID 36704329, 2022). "COL4A1 at chr13q34 was shared between migraine and DBP (lead SNP rs13260, PCPASSOC = 8.69 × 10−15 based on SHet statistic) as well as PP (lead SNP rs12875271, PCPASSOC = 6.29 × 10−12 based on SHet statistic)." (PMID 32632093, 2020). "Additionally, COL4A1 pathogenic variants are associated with SVD, which shares features with migraine." (PMID 40869943, 2025).